IL6 (interleukin 6)
Diseases named in the same sentence as IL6 in open-access papers (continued):
Sharing a sentence is not in itself a finding about the gene and the disease.
hepatocellular carcinoma (continued). "Recent data indicate that IL-6 may interfere with IL-27 functions due to the induction of SOCS3 expression, which inhibits IL-27-mediated STAT signaling, in hepatocellular carcinoma cells." (PMID 29020964, 2017). "The Morris-7777 hepatoma tumor model is characterized by anorexia and the absence of pro-inflammatory cytokines such as interleukin-6 (IL-6) or tumor necrosis factor-α (TNF-α) but elevated macrophage-inhibitory cytokine-1 (MIC-1)." (PMID 28475119, 2017). "IL-6/STAT3-mediated CSC marker, CD133 up-regulation contributes to promotion of liver carcinoma." (PMID 28507278, 2017). "A negative correlation between secreted IL-6 and SC adipogenic capacity was apparent, perhaps consequent to IL-6 repression of CEBPα expression in hepatoma cells." (PMID 27342408, 2016). "This study aimed to explore the responses to the interleukin-6 (IL-6)/soluble interleukin-6 receptor (sIL-6R) complex in peritumoral endothelial cells (PECs) and tumor endothelial cells (TECs), as well as determine the signaling pathways in the angiogenesis of hepatocellular carcinoma (HCC)." (PMID 26525581, 2015). "Therefore, vIL-6 mimics biological properties of cellular IL-6, such as supporting cell growth of the IL-6-dependent cell lines B9 or INA-6 and inducing acute-phase gene expression in a hepatocellular carcinoma cell line." (PMID 23301033, 2013). "In addition to JAK-1, IL-6/JAK-2/STAT3 activation and tumor progression in hepatocellular carcinoma has recently been reported." (PMID 23555719, 2013). "IL-6 and TNF null mice have decreased production of hepatic lipid and macrophage infiltration when fed a high-fat diet, resulting in the suppression of steatohepatitis and hepatocellular carcinoma (HCC) formation." (PMID 27335818, 2013). "In the present study, we discovered that cytokines secreted by TAECs including IL-6, IL-8, MCP-1 and GRO-α were up-regulated after insufficient RFA, which may explain the enhanced invasiveness ability of hepatoma cells." (PMID 23171368, 2012). "Hepatocellular carcinoma (HCC) is more common in males and one reason for this difference may be higher interleukin-6 (IL-6) levels in males." (PMID 23226157, 2012). "Concomitant overexpression of IL6 and IL6Rα in double transgenic mice is sufficient to induce hepatocellular carcinomas and administration of Hyper-IL6, but not IL6, increased colonic tumours in CAC-challenged wild-type mice." (PMID 20478049, 2010). "Furthermore, the incidence of hepatocellular carcinoma in humans, or in DEN- and CAC-induced tumours in mice, is less prominent in females due to the capacity of estrogen to suppress IL6 transcription." (PMID 20478049, 2010). "In this study, we found that IL-6 was able to effectively suppress hepatitis B virus (HBV) replication and prevent the accumulation of HBV covalently closed circular DNA (cccDNA) in a human hepatoma cell line." (PMID 19374779, 2009). "Thus, the induction of hepcidin by IL-6 and BMP-2 in the two hepatoma cell lines was reproducible, dose-dependent and mediated by the proximal promoter region, in agreement with previous studies." (PMID 19924283, 2009). "This study highlights the critical role of IL-6, IL-10, and liver function markers (AST and ALT) in the progression and prognosis of hepatocellular carcinoma (HCC)." (PMID 41379186, 2025). "It was discovered that CAFs from hepatocellular carcinoma impact T cell development and function, as well as the patient’s overall longevity, by enticing monocytes to the TME by releasing CXCL12 and driving them to transform into MDSCs by activating STAT3 through IL-6." (PMID 37007004, 2023). "In addition, NLRC3 silencing may play an important role in cancer progression and prognosis of hepatocellular carcinoma via the activation of Janus kinase 2/signal transducers and the transcription 3 (JAK2/STAT3) pathway under interleukin-6 (IL-6) stimulation." (PMID 37964222, 2023).
hepatocellular carcinoma (continued). "However, in a recent RCT where patients with hepatocellular carcinoma received probiotics preoperatively, the IL-6 levels after hepatectomy were not statistically different between the control and the probiotic group." (PMID 36986061, 2023). "Additionally, this research demonstrates that CKLF1 mediated its oncogenic effects through the IL-6/STAT3 signaling pathway and could assist in the staging and prognostic assessment of patients with hepatocellular carcinoma." (PMID 36865551, 2023). "In a study on HCC, TAM-released IL-6 promoted the progression of hepatocellular carcinoma stem cells through STAT3 signaling." (PMID 35733919, 2022). "Specifically, the overexpression of HBx in hepatic and hepatoma cell lines activates TLR4 downstream signaling components such as myeloid differentiation primary response 88 (MyD88), IRAK1, and nuclear factor-kappaB (NF-κB), contributing to the secretion of IL-6, a major pro-inflammatory cytokine." (PMID 36298831, 2022). "MiR-132 also inhibits proliferation in hepatocellular carcinoma (HCC) by inactivating the AKT / mTOR signaling pathway, and by inhibiting IL1β and IL6 expression through inhibition of the transcriptional co-activator P300." (PMID 33539381, 2021). "In the present study, we observed that serum values of five biomarkers (namely, AFP, PIVKA-II, GPC-3, adiponectin and IL-6) were significantly different between patients with and without hepatocellular carcinoma; the best accuracy for the detection of tumor was achieved by PIVKA-II." (PMID 34064999, 2021). "Blocking either CAF IL-6 or myeloid STAT3 can disrupt signaling from CAFs to myeloid cells and attenuate immunosuppression in hepatocellular carcinoma (HCC) and pancreatic cancer." (PMID 33370234, 2020). "STAT3 protein together with IL6, HNF4A, HNF1A, and three microRNAs constructed a feedback loop, which regulates oncogenesis of hepatocellular carcinoma (HCC)." (PMID 31219249, 2019). "Therefore, we concluded that preoperative sera IL6, IL8, and TNF-α may predict the postoperative recurrence of hepatocellular carcinoma." (PMID 31781194, 2019). "There may be differences in the upstream events in different cell types because IL-6 alone did not phosphorylate MKK4 in the mouse hepatoma cells as it did in human HepG2 cells." (PMID 31554244, 2019). "Another research showed that addition of IL-6 could significantly decrease the percentage of Treg cells and simultaneously increase the proliferation ability and cytotoxicity of the CIK cells against hepatocellular carcinoma (HCC) in vitro." (PMID 28729866, 2017). "Interleukin-6 (IL-6), a growth factor for bile duct epithelium, has a sensitivity as high as 100% in diagnosing CCA, but a low specificity, considering its elevated levels in hepatocellular carcinoma, benign biliary disease, and metastatic lesions, limiting its specificity." (PMID 28077782, 2017). "This study provides further evidence that IFN-λ activates the Stat 3–HFN 4α–miR-122 circuit independent of IL-6, which may be important for the development of hepatocellular carcinoma due to chronic inflammation." (PMID 26657215, 2015). "Correlation among mediators (IL-6, IL-27, TNF-α, and VEGF) with STAT proteins at diverse clinical-pathologic stages of hepatocellular carcinoma (HCC) remains limited." (PMID 25908103, 2015). "In a hepatocellular carcinoma (HCC) model, it was shown that TAM secrete IL-6 activating STAT3 in HCC cells and promoting expansion of cancer stem cells." (PMID 26074923, 2015). "Neither TNF-α nor IL-6 was detected in supernatants of hepatoma 22a cells by ELISA." (PMID 21760797, 2011). "Moreover, preliminary experiments showed that DP did not induce IL-6 in hepatoma cells, which was a further candidate mediator of hepcidin expression." (PMID 19924283, 2009).
hepatocellular carcinoma (continued). "Hepatocellular carcinoma (HCC) is another inflammation-driven cancer, where inflammatory cytokines such as TNF-α and IL-6 activate downstream targets including NF-κB, JNK, and STAT3, thereby promoting tumorigenesis." (PMID 40051564, 2025). "AKR1C3 participates in NF-κB signaling and IL6/STAT3 pathway, resulting in cell proliferation and metastasis in hepatocellular carcinoma (HCC) cells, while treatment with the AKR1C3 inhibitors could suppress tumor growth and promote cell death." (PMID 40603306, 2025). "In hepatocellular carcinoma (HCC), LPS promotes cell survival, proliferation, invasion, and production of pro-inflammatory mediators, including TNF-α, iNOS, IL-1β, IL-6, CCL-2, CCL-22, vimentin, and epidermal growth factor receptor (EGFR), through the induction of TLR4 signaling." (PMID 40444051, 2025). "Previous studies have shown that high levels of IL-6 in the TME of highly invasive breast cancer and hepatocellular carcinoma (HCC) have a positive effect on cancer cell growth and metastasis, as well as on the attenuation of natural killer (NK) cell immune surveillance." (PMID 40430040, 2025). "Furthermore, cell culture experiments showed that even isolated egg proteins alone are sufficient to induce expression of MCM7 in human hepatoma cells without the involvement of the generally accepted paracrine-triggered mechanism by mitogens such as interleukin 6 and EGF." (PMID 37696392, 2024). "In addition, NF-κB induces the release of the inflammatory factor IL-6, leading to the signal transducer and activator of STAT3 activation, which promotes hepatocyte repair and replication capacity and inhibits apoptosis, thereby promoting the development of hepatocellular carcinoma." (PMID 38313314, 2024). "Remarkably, CAFs-derived IL-6 upregulates PD-L1 expression by activating the JAK-STAT3 signaling pathway of TANs, ultimately impairing T cell function and inducing immune tolerance in hepatocellular carcinoma(HCC)." (PMID 36759842, 2023). "Our results demonstrated that cryptolepine inhibits the IL-6/STAT3 signalling pathway, and therefore cryptolepine-based remedies such as Cryptolepis sanguinolenta could potentially be used as an effective immunotherapeutic agent for hepatocellular carcinoma and other cancers." (PMID 34078370, 2021). "In line with this, the STAT3/IL-6 pathway was reported to be involved in the increased frequency of CD44+ hepatocellular carcinoma (HCC) stem cells, when co-cultured with TAMs isolated from HCC-bearing patients." (PMID 32397392, 2020). "However, neither IL-6 nor TNFα could induce PD-L1 expression on hepatoma cells, with or without EZH2-silencing." (PMID 31727135, 2019). "Moreover, α-SMA+ CAF-derived IL-6 can recruit neutrophils, activate signal transducer and activator of Janus kinase-programmed cell death ligand 1 (STAT3-PDL1) signaling cascade in neutrophils, therefore, contributing to immunosuppression in hepatocellular carcinoma." (PMID 31462327, 2019). "In hepatocellular carcinoma (HCC), activated HSCs induce phenotypic changes in oncogenic hepatocytes, notably through the production of growth factors and cytokines such as HGF (hepatocyte growth factor) and IL6 in favor of tumor cell proliferation." (PMID 29855567, 2018). "This study aimed to determine the expression of progranulin (PGRN) in hepatocellular carcinoma (HCC) cells in response to interleukin 6 (IL-6), a non-cellular component of the tumor microenvironment, and the molecular mechanism of PGRN oncogenic activity in hepatocarcinogenesis." (PMID 26879559, 2016). "Irradiation significantly upregulated the mRNA expressions of FasL, TRAIL, TNF-α, and TGF-β1 in hepatoma cells, and downregulated the mRNA expressions of IGF-1 and PDGFB, but no obvious effects on the expressions of VEGFA, PDGFA, and IL-6." (PMID 27431384, 2016).
hepatocellular carcinoma (continued). "By contrast, the negative coefficient for FUT8 implies a reduction in alpha-1,6 fucosylation (core fucosylation) after IL-6 stimulation, which does not contradict our previous finding that FUT8 overexpression does not facilitate cellular fucosylation in hepatoma cells." (PMID 36313594, 2022). "BM-MSCs might activate the IL6/STAT3 signaling pathway and promote cell invasion in hepatocellular carcinoma, but the immunomodulatory role of BM-MSCs on IL17A/IL6/STAT3 was not fully elucidated in liver fibrosis." (PMID 30346985, 2018). "Unlike in MCD, multiple cytokines such as IL-6, TNF-α and IL-1 are involved in the pathogenesis of RA-anemia, and we therefore analyzed the effects of cytokine combinations on hepcidin production in hepatoma cells." (PMID 24286116, 2013). "It should be noted, however, that we did not observe any upregulation of the major drivers of hepatocellular carcinoma (HCC) (MYC, IL6, β-catenin) in SO-HFD, nor any signs of tumors or neoplastic lesions." (PMID 26200659, 2015).
pneumonia (577 papers, 2005 to 2026). An acute, acute and chronic, or chronic inflammation focally or diffusely affecting the lung parenchyma, caused by an infection in one or both of the lungs (by bacteria, viruses, fungi, or mycoplasma.). "Zinc deficiency can also contribute to elevated FPP levels in pneumonia because the acute-phase response, driven by proinflammatory cytokines (IL-6, IL-1β, TNF-α), triggers metallothionein synthesis and sequesters zinc in the liver and immune cells." (PMID 40615660, 2025). "The univariate logistic regression analysis revealed that age (over 60 years), CRP, IL-6, D-dimer, hemoglobin concentrations, and platelet count were associated with an increased risk of pneumonia." (PMID 40969806, 2025). "Our nomogram confirmed that fever duration and WBC, IL-6, and D-dimer levels are risk factors for pneumonia complicated by NP." (PMID 40399899, 2025). "Unlike IL6R missense variants linked to bacterial infections, the IL6 instrument was associated with lower risk of pneumonia hospitalization." (PMID 40858837, 2025). "IL-6 serum levels were higher in individuals with SARS-CoV-2-associated pneumonia, linked to the disease severity and mortality." (PMID 40895576, 2025). "Conversely, and in line with previous literature, proxied IL-6 inhibition was associated with an increased odds of developing pneumonia (OR 1.21, 95% CI 1.07–1.38)." (PMID 40819633, 2025). "While serum IL-6 levels were highest in patients with pneumococcal pneumonia and pneumonia caused by a Legionella species, serum TNF levels were higher in the majority of patients, regardless of the etiology." (PMID 40136649, 2025). "IL-6 signaling downregulation via IL6 perturbation was associated with a lower risk of pneumonia hospitalization, in contrast to associations of IL6R missense variants with a higher risk of bacterial infections." (PMID 40858837, 2025). "In this patient, plasma IL-6 increased significantly at the outset of myocarditis, hepatitis, and pneumonia, while IL-10 increased exclusively at the onset of pneumonia, suggesting that both were associated with the development and regression of irAEs." (PMID 39139287, 2024). "In this study, the SLN formulation of DXMS-Pal (DXMS-Pal-SLNs) was developed and evaluated in reducing the secretion of pro-inflammatory cytokines, namely TNF-α and IL-6, mainly by alveolar macrophages for pneumonia-associated inflammation treatment." (PMID 39065575, 2024). "Taken together the most important findings are that a lower level of haemoglobin, higher levels of post-surgery interleukin 6 and leukocytes as well as suffering from pneumonia and a limited mobility postoperatively increased the risk of POD significantly." (PMID 39112758, 2024). "Concerning pneumonia, enhanced FEV1 (OR per SD = 0.93 [95% CI: 0.88, 0.98]) and FVC (OR per SD = 0.94 [95% CI: 0.88, 1.00]) lowered the infection risk, whereas elevated CRP, IL-6, and monocyte count magnified the risk of pneumonia." (PMID 39337223, 2024). "In 2020, Ulhaq and Soraya observed a substantial correlation (p = 0.019) between IL-6 174G/C polymorphism and the severity of pneumonia specifically in the Caucasian population." (PMID 39354444, 2024). "There is a trend toward higher IL-6 production among the allele C carriers as well as an association of this allele with more severe forms of pneumonia in general, as previously suggested in a recent meta-analysis." (PMID 37243282, 2023). "A cytokine storm in the lungs caused by RSV infection leads to severe pneumonia, in which the inflammatory factors interleukin-6 (IL-6) and interferon-γ (IFN-γ) are considered to be the main markers of severe RSV infection." (PMID 37764214, 2023). "Our results further revealed that among patients with pneumonia-associated bacteremia, those who died within 28 days exhibited significantly higher levels of IL-6, a higher rate of antifungal drug usage, and prolonged mechanical ventilation." (PMID 37768395, 2023).